CDK2 (cyclin dependent kinase 2)
Diseases named in the same sentence as CDK2 in open-access papers (continued):
Sharing a sentence is not in itself a finding about the gene and the disease.
medulloblastoma (8 papers, 2015 to 2025). A malignant, invasive embryonal neoplasm arising from the cerebellum. "Their use in combination with CDK2 inhibitor is being studied in MYC-driven medulloblastoma." (PMID 34638300, 2021). "The decrease in the expression levels of proliferation-related targets of miR-193a like E2F1, CCND1, and several other cell cycle regulators like CDK2, CCND2 is consistent with the growth inhibition of medulloblastoma cells upon the expression of miR-193a." (PMID 32410663, 2020). "Given that Paullones, including alsterpaullone, have been identified as CDK1/CDK2/CDK5 and GSK3B inhibitors, we examined the gene expression profiles of the CDK genes in the Group 3 medulloblastoma cell lines." (PMID 26061748, 2015).
nasopharyngeal carcinoma (8 papers, 2020 to 2025). A carcinoma arising from the nasopharyngeal epithelium. "The results showed that icaritin downregulated the expression of cyclin D1, CDK2, and CDK4 in a dose-dependent manner, further demonstrating that icaritin caused S-phase arrest in nasopharyngeal carcinoma cells." (PMID 36467051, 2022).
oral cancer (8 papers, 2018 to 2025). "Previous studies have reported that increased expression of CDK2 is a critical factor for the progression of oral cancer and can be used as a predictive marker for poor prognosis." (PMID 36768994, 2023). "Our findings revealed that targeting DNMT1 in oral cancer cells resulted in near-complete genome-wide DNA hypomethylation, triggering the dual attenuation of PI3K-AKT and CDK2-Rb and collaborative phosphorylation of GSK3β." (PMID 38755637, 2024). "We document the molecular docking analysis data of piperine with the cell cycle proteins such as CDK2, CDK4, Cyclin D and Cyclin T for further consideration to combat oral cancer." (PMID 32831516, 2020). "Cyclin-Dependent Kinase 2(CDK2) has been attributed with certain cancer progressions, especially the oral cancer." (PMID 29514608, 2018). "Additionally, capsaicin-induced a G0/G1 phase arrest in oral cancer cells through the reduction of cyclin-D (CCND), cyclin-dependent kinase 2 (CDK2), and cyclin-dependent kinase 6 (CDK6), and an increase in the levels of p21 and p16." (PMID 35600864, 2022). "A preclinical study of oral carcinoma cell lines, Ca9-22, HSC-2, HSC-3, HSC-4, demonstrated that Kaempferol and withanolide D kaempferol and withanolide D effectively inhibited oncogenic proteins, CDK2, and BRD3, inducing cytotoxicity via autophagy and caspase activation." (PMID 41346617, 2025). "Therefore, it is of interest to understand the molecular docking interactionsof piperine with several cell cycle proteins such as Cyclin dependent kinase 2 (CDK2), Cyclin-dependent kinase 4 (CDK4), Cyclin D and Cyclin T for further consideration in drug discoveryrelated to oral cancer." (PMID 32831516, 2020).
endometrial cancer (7 papers, 2012 to 2025). Primary or metastatic malignant neoplasm involving the endometrium (mucous membrane that lines the endometrial cavity). "Despite the broad role of CDK2 in the cell cycle, only cluster 3, largely comprising of ovarian and endometrial cancer cell lines, exhibited exclusive vulnerability to CDK2 and CCNE1 depletion." (PMID 39924553, 2025). "The CDK2 alterations (127; 1.2%) occur in 22 cancer types, mostly in endometrial carcinoma (4.1%), esophagogastric carcinoma (3.11%), and ovarian epithelial tumor (2.91%)." (PMID 33668805, 2021). "Therefore, the miR-372/RhoC pathway and the miR-372/Cyclin A1 and CDK2 pathway may collectively be involved in the anti-oncogenic properties of miR-372 in endometrial carcinoma." (PMID 26673619, 2016). "Overexpression of lncRNA ABHD11‐AS1 promoted the proliferation, G1‐S progression, invasion and migration of endometrial cancer cells; inhibited apoptosis; up‐regulated cyclin D1, CDK1, CDK2, CDK4, Bcl‐xl and VEGFA; and down‐regulated p16, while ABHD11‐AS1 down‐regulation has the opposite effect." (PMID 29799152, 2018).
esophageal squamous cell carcinoma (7 papers, 2015 to 2024). Esophageal squamous cell carcinoma (ESCC) is a type of esophageal carcinoma (EC) that can affect any part of the esophagus, but is usually located in the upper or middle third. "It was previously reported that miR-200b-3p reduces CDK2 expression, causing G2/M-phase arrest in esophageal squamous cell carcinoma cells." (PMID 29156719, 2017). "Moreover, depletion of S6 results in a sharp decrease of cyclin D1 and CDK2 levels to regulate cell viability in esophageal squamous cell carcinoma." (PMID 28212559, 2017). "It was suggested that Smad3-P27/P21-cyclin E1/CDK2-phosphorylated retinoblastoma protein pathways might be involved in IGFBP-3-mediated radiosensitivity transition in esophageal squamous cell carcinoma (ESCC) the most prevalent histologic type of esophageal cancer in China and eastern countries." (PMID 27978831, 2016). "It suggested that IGFBP-3 promoted esophageal squamous cell carcinoma (ESCC) cell cycle transition from G0/G1 to S phase via Smad3-P27/P21-cyclin E1/cyclin-dependent kinase (CDK2)–phosphorylated retinoblastoma protein (pRb) pathway signaling." (PMID 26670461, 2015).
head and neck squamous cell carcinoma (7 papers, 2014 to 2025). A squamous cell carcinoma that arises from any of the following anatomic sites: lip and oral cavity, nasal cavity, paranasal sinuses, pharynx, larynx, and salivary glands. "Sidransky group found that kinases including ATM, CDK2, and p70s6K can phosphorylate ΔNp63α in HNSCC (head and neck squamous cell carcinoma) cells upon DNA damage." (PMID 24822180, 2014).
lymphoma (7 papers, 2002 to 2024). A malignant (clonal) proliferation of B- lymphocytes or T- lymphocytes which involves the lymph nodes, bone marrow and/or extranodal sites. "Previous studies have shown that CNF2024 induced G2 cell cycle arrest in Hodgkin’s lymphoma cells and decreased cell cycle-related proteins, including CDK1, CDK2, and cyclin D3, along with either G1 or G2 cell cycle arrest in multiple lymphoma cell lines." (PMID 38794139, 2024). "A high RIS score was also reported for the positive regulation of the reactive oxygen species (ROS) metabolic process pathway (GO:2000379) associated with the DB cell line (lymphoma) when administered with Dinaciclib (an inhibitor of CDK1, CDK2, CDK5, and CDK9)." (PMID 37432499, 2023).
oral squamous cell carcinoma (7 papers, 2019 to 2025). "Additionally, the spliced variants of cyclin-dependent kinases 2 (CDK2) and transmembrane receptor for hyaluronic acid CD44 were both manipulated by hnRNPA1 to drive the development of oral squamous cell carcinoma (OSCC) and metastatic BC." (PMID 35879279, 2022). "For instance, in oral squamous cell carcinoma, DNMT1 knockdown induces global hypomethylation, inactivating PI3K-AKT and CDK2-Rb signaling, and cooperating with GSK3β inactivation to suppress tumorigenicity." (PMID 41381440, 2025). "Similarly, it was reported that Yap1 formed complex with TEAD4 in the nuclei regulating the transcriptions of G1 arrest-related genes, such as CCND1, CCNE, CDK2, CDK4, and CDK6, in human oral squamous cell carcinomas." (PMID 31455378, 2019).
skin cancer (7 papers, 2016 to 2023). "In humans, cyc-B and cdk2 kinase influence a cell’s progress through the cell cycle, which is especially important in several skin cancers." (PMID 26989617, 2016). "Interestingly, it was reported that in A431 skin cancer cells, EGCG did not alter the levels of p27, CDK2, and Cyclin D1 but did show inhibition of cell growth in vitro by increasing p21 and a decrease in CDK4." (PMID 37960113, 2023).
thyroid cancer (7 papers, 2010 to 2025). "NVP-BEZ235 treatment significantly decreased the protein expression of cyclin E1 and Cdk2 in the human thyroid cancer cell lines in a time-dependent manner." (PMID 32025215, 2020). "Our data showed that SFN-treated thyroid cancer cells were arrested in G2/M phase, which was accompanied by a decline in the levels of Cdk1, Cdk2, Cyclin B1 and Cdc25C and an increase in the levels of Chk1 and p21." (PMID 26312762, 2015). "Previous studies in cancer models, including thyroid cancer, have cited a role for NF-κB in malignant cell proliferation by transcriptional regulation of cyclin D1, CDK2, cyclin E and c-Myc." (PMID 20492683, 2010). "In thyroid cancer cells, oncogene activation prevented TGF-ß/SMAD-dependent p27 repression and CDK2/SMAD3 phosphorylation, leading to p65 up-regulation, which repressed BAX, induced cyclin D1 and promoted TGF-ß-dependent growth." (PMID 37954148, 2023).
diabetes (6 papers, 2016 to 2024). "In addition, CDK2 agonists may help to restore β cell function and restart β cell proliferation to combat β cell failure in diabetes patients." (PMID 38915894, 2024). "Upregulation of CDK2, the CDC25A phosphatase and DUSP14 in diabetes-free tumors is consistent with the tumor phenotype as these genes are reportedly overexpressed to stimulate cell proliferation and invasion in CRC." (PMID 32971867, 2020). "ACC1, caspase 3, cyclin-dependent kinase 2 (Cdk2), and AMPK were reported to be involved in flavan-3-ol-mediated modulation of obesity- and diabetes-related apoptosis and ROS generation." (PMID 27092490, 2016). "Since the role of CDK2 in diabetes and DN has not been previously studied, we next investigated the expression level of CDK2 in the glomeruli of insulin resistant obese Zucker rats, a well-characterized model of T2D that shows similarities to early human DN31." (PMID 26876672, 2016).
esophageal cancer (6 papers, 2016 to 2024). A primary or metastatic malignant neoplasm involving the esophagus. "Accordingly, ART caused a G0/G1 phase arrest in vitro and in vivo in esophageal cancer by down-regulating CDC25A, a CDK2 activator, thereby compromising entry into the S phase." (PMID 33316936, 2020). "In conclusion, based upon our date, we found that pristimerin could induce the downregulation of cyclin E, CDK2, and CDK4 to lead to the block of G0/G1 transition, which gave rise to cell death in esophageal cancer." (PMID 31218209, 2019).
heart failure (6 papers, 2006 to 2024). Inability of the heart to pump blood at an adequate rate to meet tissue metabolic requirements. "MiR-221 acts as an important regulator of autophagy balance and cardiac remodeling by modulating the p27/CDK2/mTOR axis, and miR-221 has been implicated as a therapeutic target in heart failure." (PMID 32477928, 2020). "Cyclin-dependent kinase 2 (CDK2) is a serine/threonine kinase, and its dysregulated activation has been associated with MI and heart failure." (PMID 34301918, 2021). "Other studies have found that increased miR-221 in HOCM regulates cardiac hypertrophy through p27/cyclin-dependent kinase-2/mammalian target of rapamycin axis, thereby exacerbating heart failure." (PMID 31868204, 2020). "Previous studies have revealed that miR-221 inhibits autophagy and promotes heart failure by modulating the p27/CDK2/mTOR axis and inhibits hypoxia/reoxygenation-induced autophagy through the DDIT4/mTORC1 and TP53INP1/p62 pathways." (PMID 32477928, 2020). "It is now recognized that p27-mediated inhibition of cyclin-dependent kinase 2 represses mTOR in cardiomyocytes, that p27 can function as an anti-hypertrophic factor, and that p27 is down-regulated during heart failure and cardiac hypertrophy." (PMID 29290979, 2017). "However, loss of CDK4 and CDK2 together (but not combined loss of CDK6 and CDK2) results in suppressed pRb phosphorylation at midgestation, more severe size reduction in the different organs, embryonic lethality due to heart failure and severe impairment of embryo cell proliferation in culture." (PMID 17092340, 2006).
adenoma (5 papers, 2019 to 2024). A neoplasm arising from the epithelium. "As CDK2 protein data at large-scale levels are not available so far, we performed functional analyses on CDK2 kinase activity in a small patient cohort of proliferating HCCs with corresponding non-tumorous control tissue of different aetiologies, benign adenomas and healthy control tissue." (PMID 34830835, 2021).
Infertility (5 papers, 2015 to 2021). "Several CDK2-bound genes have also been implicated in other aspects of germ cell development, including Palb2, Pds5b, Safb1, and Herc4, or have been investigated as potential markers of infertility in human populations: Mtrr and Vdac3." (PMID 31350280, 2019). "They discovered that of these four mutated essential meiosis genes, only a cyclin-dependent kinase 2 (Cdk2) allele mimicking SNP rs3087335, which alters an inhibitory WEE1 protein kinase phosphorylation site, caused infertility." (PMID 33562517, 2021). "A Cdk2 and Cdk6 dKO also results in infertility in both sexes, while a Cdk4 and Cdk6 dKO displays the same infertility seen in a Cdk4 single KO, with total female infertility and partial male infertility, signifying that Cdk6 does not have a dominant phenotype in mouse fertility." (PMID 32731332, 2020). "Loss of Cdk2 results in infertility, a dramatic increase in synapsis between non-homologous chromosomes, the appearance of fusions and ring chromosomes, and eventual arrest in pachytene due to improper telomere maintenance." (PMID 25934699, 2015).
Obesity (5 papers, 2016 to 2022). Accumulation of substantial excess body fat. "The potential association between p27 and CDK2 mRNA WAT expression with obesity and circulating biomarkers of glucose and lipid metabolism was next investigated." (PMID 34769201, 2021). "One of the limitations of the present study is that it is not possible to discern whether the alterations of the expression of p27, cdk2 or ccna/ccne in adipose tissue during aging or obesity are a consequence or cause of these processes." (PMID 34769201, 2021). "If the regulation of cdk2 and p27 during aging or in obesity is relevant for the development and function of adipose tissue depots, these should be evolutionary conserved between different species." (PMID 34769201, 2021). "Taken together, the results obtained suggest an important transcriptional regulation of p27 and cdk2 in adipose tissue during aging and obesity." (PMID 34769201, 2021). "The mRNA expression of p27 and CDK2 was analyzed in scWAT and vWAT biopsies from subjects (men and women) with normal-weight, overweight, obesity and obesity with type 2 DM." (PMID 34769201, 2021). "The aim of this study was to analyze the changes in the expression of p27 and cdk2 in different adipose tissue depots during aging, as well as their regulation by obesity in mice." (PMID 34769201, 2021). "Our data have also revealed that the long-term high fat feeding during the process of aging provoked a significant increase of the expression of p27 and cdk2 exclusively in scWAT, suggesting a likely involvement in the regulation of the expandability of this depot in obesity." (PMID 34769201, 2021). "Thus, we aimed to analyze the regulation of the gene expression of cdk2, p27, ccna and ccne in different adipose tissue depots during aging, as well as in obesity in mouse models." (PMID 34769201, 2021). "Similarly, CDK2 was also slightly increased in human scWAT in obesity which was also observed in the same depot of DIO mice." (PMID 34769201, 2021). "In this study, we characterized the differential expression of several cell cycle regulators (p27, cdk2, ccna and ccne) between the different fat depots, as well as their regulation during aging and obesity and their potential implications in these physiological/pathophysiological situations." (PMID 34769201, 2021). "Taken together, these results show a differential adipose depot-dependent regulation of p27 and cdk2 in aging and obesity, suggesting that p27 and cdk2 could contribute to the adipose-tissue depot’s metabolic differences." (PMID 34769201, 2021). "Metformin increases m6A methylation levels of CCND1 and CDK2 by inhibiting FTO expression, thereby inhibiting adipogenesis and combating obesity." (PMID 36461116, 2022). "Changes in the expression of p27 and CDK2 in visceral and subcutaneous white adipose tissue (WAT) biopsies were also analyzed in a human cohort of obesity and type 2 diabetes." (PMID 34769201, 2021). "Obesity upregulates p27 and cdk2 expression in scWAT, but not in other fat depots of aged mice." (PMID 34769201, 2021). "Moreover, m6A-YTHDF2-FTO signaling way might be crucial for the development of obesity, m6A—binding protein YTHDF2 can methylate mRNAs of cyclin A2 (CCNA2) and cyclin dependent kinase 2 (CDK2), and then reduce their protein expression to prolong cell cycle progression and suppress adipogenesis." (PMID 32110378, 2020).
ovarian tumors (5 papers, 2015 to 2024). "At the transcriptomic level, we observed a significantly higher expression of CDK2 in the ovarian tumour tissues compared to the normal tissues." (PMID 38612869, 2024). "Cyclin D1 was overexpressed in 18% of serous epithelial ovarian cancer and associated with a more aggressive tumor phenotype and poor prognosis, whereas CDK2 was shown to be amplified in a relatively small proportion (6.4%) of ovarian tumors." (PMID 32862831, 2020). "For example, E2 increased expression of the cyclin dependent kinase 2 (Ccnd2) gene, which is altered (via amplification or mRNA upregulation) in 12 % of ovarian tumors, and has been shown to be upregulated in some OVCAs." (PMID 26879975, 2016). "In conclusion, our study has laid a foundation on using currently available Cdk2 inhibitor for ovary tumors that exhibit elevated CCNE1 expression." (PMID 26204491, 2015). "The objective of this study was to investigate the potential of Cdk2 inhibitor to suppress ovary tumor progression." (PMID 26204491, 2015). "This study suggests that ovary tumors with elevated CCNE1 expression may be staged for Cdk2-targeted therapy." (PMID 26204491, 2015). "As ovary tumors with elevated CCNE1 level often exhibit higher Cdk2 expression and most of CCNE1-associated tumor promoting effects require the participation of Cdk2, we reasoned that targeting Cdk2 may be an attractive alternative given the current availability of small molecule Cdk2 inhibitors." (PMID 26204491, 2015).
psoriasis (5 papers, 2021 to 2024). An autoimmune condition characterized by red, well-delineated plaques with silvery scales that are usually on the extensor surfaces and scalp. "In psoriasis, altered distributions can be seen in cell cycle regulatory proteins, CDK2 and cyclin E expression, which cause hyperproliferation and are upregulated in the upper layers of the epidermis." (PMID 35008548, 2021). "WTAP contributes to the pathogenesis of psoriasis by promoting keratinocyte proliferation via the induction of cyclinA2-mediated and CDK2-mediated cell cycle progression." (PMID 38874470, 2024). "Similarly, cyclin D1, CDK2, and CDK4 expression is increased in psoriatic lesions of psoriasis patients." (PMID 34639115, 2021).
renal carcinoma (5 papers, 2019 to 2021). A carcinoma arising from the epithelium of the renal parenchyma or the renal pelvis. "In the present study, apart from SKCM, kidney renal papillary cell carcinoma exhibited CDK2, CDK4, KIT, and VWF Cox coefficient values of > 0, indicating that the high expression of these four key genes is a risk factor for patients with renal carcinoma." (PMID 34582363, 2021).